EFNA4 (ephrin A4)
Description:
Cell surface GPI-bound ligand for Eph receptors, a family of receptor tyrosine kinases which are crucial for migration, repulsion and adhesion during neuronal, vascular and epithelial development. Binds promiscuously Eph receptors residing on adjacent cells, leading to contact-dependent bidirectional signaling into neighboring cells. May play a role in the interaction between activated B-lymphocytes and dendritic cells in tonsils.
Synonyms: LERK-4; EPLG4; LERK4; EFL4
Tractability: Antibody: UniProt places it where antibodies can reach, with high confidence; its Gene Ontology location is reachable by antibodies, with high confidence; UniProt predicts a signal peptide or a membrane-spanning region. PROTAC: ubiquitination databases record sites on it.
Gene: Protein-coding gene on chromosome 1 (155,063,737 to 155,069,553, forward strand). Ensembl gene ENSG00000243364.
Subcellular location: Cell membrane (Isoform 1); Secreted (Isoform 2)
Pathways (Reactome):
Developmental Biology: EPH-Ephrin signaling; EPH-ephrin mediated repulsion of cells; EPHA-mediated growth cone collapse
Gene Ontology:
Molecular function: ephrin receptor binding; protein binding; transmembrane-ephrin receptor activity
Biological process: axon guidance; cell-cell signaling; ephrin receptor signaling pathway; cell communication; signaling
Cellular component: plasma membrane; extracellular region; membrane
Genetic constraint (gnomAD): Loss-of-function variants: 22 observed, 23.59 expected, observed/expected ratio (o/e) 0.93, 90% interval 0.67 to 1.33. The upper end of that interval is the gene's LOEUF score, 1.33, which puts it in group 5 of 6, group 1 being the genes least tolerant of losing a copy. Missense variants: 252 observed, 245.82 expected, observed/expected ratio (o/e) 1.03, 90% interval 0.92 to 1.14. Synonymous variants: 113 observed, 106.34 expected, observed/expected ratio (o/e) 1.06, 90% interval 0.91 to 1.24.
Homologues: Orthologues: chimpanzee EFNA4 (100% identical), pig EFNA4 (88% identical), rabbit EFNA4 (88% identical), guinea pig EFNA4 (87% identical), dog EFNA4 (86% identical), rat Efna4 (85% identical), mouse Efna4 (84% identical), tropical clawed frog efna4 (52% identical), Drosophila melanogaster Ephrin (23% identical), Caenorhabditis elegans efn-4 (22% identical), Caenorhabditis elegans vab-2 (22% identical), Caenorhabditis elegans efn-2 (21% identical), and 1 more. Paralogues in human: EFNA3 (43% identical), EFNA2 (40% identical), EFNA5 (40% identical), EFNA1 (36% identical), EFNB1 (22% identical), EFNB2 (21% identical), EFNB3 (21% identical).
Diseases named in the same sentence as EFNA4 in open-access papers:
EFNA4 is named in the same sentence as 56 diseases in open-access papers, as found by Europe PMC text mining. Sharing a sentence is not in itself a finding about the gene and the disease. The quoted sentences say what the papers report.
breast carcinoma (9 papers, 2015 to 2022). "Bioassay studies demonstrated that EFNA1, EFNA3, and EFNA4 expression were higher in breast cancer than in normal tissues, while EFNA5 showed an opposite trend." (PMID 35309935, 2022). "High expression of EFNA4 often reveals poor OS and recurrence-free survival in breast cancer." (PMID 35309935, 2022). "Furthermore, anti-ephrin-A4-Calicheamicin (PF-06647263) has been tested on 60 patients, the majority of whom were diagnosed with ovarian or breast cancer." (PMID 34445116, 2021). "EFNA4 regulates stem cell properties in glioma, whereas EFNA5 regulates the phenotype of breast cancer stem cell-like cells." (PMID 35945523, 2022). "In the UALCAN database, the mRNA expression of EPHA1, EPHA10, EFNA1, EFNA3, and EFNA4 was significantly higher, whereas that of EPHA2, EPHA4, EPHA5, and EFNA5 was significantly lower in breast cancer tissues than in paracancerous tissues." (PMID 33977106, 2021). "EFNA4 was predicted to have poor OS and RFS in breast cancers, especially in luminal B, basal-like subtype, and patients treated with adjuvant chemotherapy." (PMID 33977106, 2021). "Protein analysis of normal organs, primary breast tumor specimens and TNBC PDX tumor models demonstrated that EFNA4 was elevated in TNBC vs. normal tissues and other subtypes of breast cancer." (PMID 30984612, 2019).
ovarian carcinoma (6 papers, 2020 to 2025). A malignant neoplasm originating from the surface ovarian epithelium. "Anti-EFNA4 ADCs represent an innovative therapeutic strategy targeting EFNA4, a protein often overexpressed in various cancers, including ovarian cancer." (PMID 41347223, 2025). "Ephrin-A4, which is overexpressed in TNBC and ovarian cancer, was selected as a therapeutic target, and a cell line transfected with the ephrin-A4 gene was challenged with two versions of biotinylated anti-ephrin-A4 coupled to Streptavidin-ZAP." (PMID 36977072, 2023). "TATs highly expressed in cervical cancer include CEACAM5, CD71, CD138, FGFR3, LYPD3, CEACAM6, etc.; VEGF is also highly expressed in ovarian cancer; CD71 and CD138 are highly expressed in endometrial cancer; the TATs highly expressed in uterine sarcoma include B7-H3, DLK1, and EFNA4." (PMID 40046734, 2025).
hepatocellular carcinoma (4 papers, 2021 to 2024). A malignant tumor that arises from hepatocytes. "The present evidence indicates that signaling by EPHA2 and its ligand, EFNA4, promotes hepatocellular carcinoma cell migration and the combination of EFNA4 and EPHA10 promotes proliferation and migration in oral squamous cell carcinoma cells." (PMID 36077763, 2022). "EFNA4 has also been reported to be involved in the proliferation of oral squamous cell carcinoma, hepatocellular carcinoma and gastric cancer." (PMID 36077763, 2022). "EFNA4 potentially promotes hepatocellular carcinoma invasion and migration via the GSK3β signaling pathway, and is involved in the invasion of glioma via Akt signaling." (PMID 35945523, 2022). "However, the role of EFNA4 in the development of hepatocellular carcinoma (HCC) has not been reported yet, and the upstream and downstream regulation of EFNA4 remain unclear." (PMID 34484860, 2021).
lung carcinoma (4 papers, 2021 to 2025). "Based on cancer genomic analysis, EFNA4 overexpression is associated with lung cancer lymph node metastasis." (PMID 36077763, 2022). "Additionally, tumor survival analysis revealed significant impact of EFNA4 expression on survival, and EFNA4 overexpression is linked to poorer lung cancer outcome." (PMID 36077763, 2022). "High levels of EFNA4 promote lung tumour cell proliferation and migration, and EFNA4 plays an oncogenic role in promoting lung cancer lymph node metastasis." (PMID 41162582, 2025). "Based on the prognosis and survival analysis, EFNA4 would be a novel biomarker to predict the progression of lung cancer patients." (PMID 36077763, 2022). "Here, we performed genome-wide DNA copy number analysis, and identified a novel lung-cancer-metastasis-related gene, EFNA4." (PMID 36077763, 2022). "First, this study provides the first bioinformatics and also experimentally validated link between EFNA4 and lymph node metastases in lung cancer." (PMID 36077763, 2022). "We reported here the results of a systematic cancer genome analysis, and EFNA4 locus amplification was identified as one of the somatic DNA alterations that exerted a potent lung cancer driving function." (PMID 36077763, 2022). "Thus, we speculated that EFNA4 is a novel lung-cancer-metastasis-associated gene." (PMID 36077763, 2022). "Together, these results identified a novel oncogenic driving function of EFNA4 in lung cancer metastasis, and implicate EFNA4 as a potential target in lung cancer therapy." (PMID 36077763, 2022). "This study provides new insights into the link between EFNA4 and lung cancer metastasis." (PMID 36077763, 2022). "Third, EFNA4 could be a prognostic marker which can be used to evaluate a lung cancer patient’s clinical outcome." (PMID 36077763, 2022). "Together, our work suggests that EFNA4 may be a potential therapeutic target and prognostic marker in lung cancer." (PMID 36077763, 2022). "Additionally, we experimentally show that EFNA4 promotes the growth and migration of lung cancer cells, and knockout of EFNA4 leads to the inhibition of lung tumor cell proliferation and migration." (PMID 36077763, 2022). "To further investigate the mechanism of lung cancer lymph node metastasis, we performed cancer genome analysis and found that EFNA4, a member of the ephrin (EPH) family, is amplified and up-regulated in lung tumor patients, especially in patients with lymph node metastases." (PMID 36077763, 2022). "The EFNA4 genome locus was significantly amplified, and EFNA4 mRNA expression was significantly up-regulated in lung cancer compared with normal lung tissue, and also in lung cancer with lymph node metastases compared with lung cancer without metastasis." (PMID 36077763, 2022). "Lung cancer patients with EFNA4 overexpression have poor prognosis." (PMID 36077763, 2022). "Our work suggests that EFNA4 could be targeted by therapeutic agents and be a prognostic marker for lung cancer." (PMID 36077763, 2022). "Altogether, our results suggest that the DNA amplification of the EFNA4 genome locus could play an oncogenic function in promoting lung cancer lymph node metastasis." (PMID 36077763, 2022). "Second, our experimental evidence suggests that EFNA4 may be an important player in lymph node metastasis, and targeting this protein represents a method to treat lung cancer." (PMID 36077763, 2022). "Interestingly, it was found that EFNA4 overexpression enhanced the ability of colony formation, cell proliferation, migration and cell adhesion in the lung cancer cell lines." (PMID 36077763, 2022). "The function of EFNA4 in human lung cancer remains largely unknown." (PMID 36077763, 2022). "A limitation of this study is the lack of molecular mechanisms by which EFNA4 promotes lung cancer metastasis." (PMID 36077763, 2022). "Direct experimental evidence demonstrating the function of EFNA4 in lung cancer lymph node metastasis is still lacking." (PMID 36077763, 2022).
lung carcinoma (continued). "However, the functions and mechanisms of EFNA4 in lung cancer are still not clear." (PMID 36077763, 2022).
craniosynostosis (3 papers, 2011 to 2022). Craniosynostosis is defined as the premature fusion of one or more cranial sutures leading to secondary distortion of skull shape resulting in skull deformities with a variable presentation. "Subsequent whole genome analysis in the proband’s father detected a variant in the EFNA4 gene (c.178C > T, p.His60Tyr), which has only been reported to be associated with sagittal craniosynostosis in one patient prior to this report but reported in other cranial suture synostosis." (PMID 36140816, 2022). "The findings in this family extend the genotypic spectrum of UMS, as well as the phenotypic spectrum of EFNA4-related craniosynostosis." (PMID 36140816, 2022).
gastric cancer (3 papers, 2022 to 2025). A primary or metastatic malignant neoplasm involving the stomach. "To detect the effects of ETS1 and EFNA4 on gastric cancer cells, we performed wound healing and Edu experiments." (PMID 41162582, 2025). "Our study found that TMB score and MSI was positively correlated with the expression of EFNA3 and EFNA4 in gastric cancer." (PMID 35309935, 2022). "The expression of EFNA1 (p = 1.62E-12), EFNA3 (p = 4.17E-07), and EFNA4 (p = 1.62E-12) were significantly increased in gastric cancer tissues." (PMID 35309935, 2022). "EFNA4 is highly expressed in early gastric cancer, whereas ETS1 expression is low." (PMID 41162582, 2025). "Compared with normal adjacent tissues, EFNA1, EFNA3, and EFNA4 were up-regulated in gastric cancer." (PMID 35309935, 2022). "Functional validation demonstrated that ETS1 actively suppresses EFNA4-mediated tumor suppression in gastric cancer, establishing a novel inhibitory axis in GC pathogenesis." (PMID 41162582, 2025). "In terms of the influence on the survival of patients, the expression of EFNA3 and EFNA4 were related to overall survival (OS) and disease-free survival (DFS) for patients with gastric cancer." (PMID 35309935, 2022). "Furthermore, the high expression of EFNA3 and EFNA4 indicates that it is beneficial for OS and DFS of gastric cancer, while the high expression of EFNA5 indicates a low survival rate." (PMID 35309935, 2022). "In gastric cancer, the expression of EFNA3 and EFNA4 showed a significant negative correlation with B cells." (PMID 35309935, 2022).
glioma (3 papers, 2021 to 2024). A benign or malignant brain and spinal cord tumor that arises from glial cells (astrocytes, oligodendrocytes, ependymal cells). "Analogous findings have been reported for ephrins, with increased expression of ephrin-A3 and ephrin-A4 in ependymoma cell lines, of ephrin-B1 in medulloblastoma cell lines and rhabdomyosarcoma tumor cells, and of ephrin-B2 in gliomas and rhabdomyosarcoma tumor cells." (PMID 38612645, 2024). "A poor prognosis has been documented for pediatric patients with gliomas overexpressing EPHA7, alveolar-type rhabdomyosarcomas overexpressing EPHB4, and osteosarcomas presenting ephrin-A4 cytoplasmic expression." (PMID 38612645, 2024).
liver cancer (3 papers, 2021 to 2025). An epithelial or non-epithelial malignant neoplasm that arises from the liver. "For TCGA database analysis, the results indicated that EFNA4 was significantly overexpressed in patients with liver cancer, and this overexpression was linked to a worse clinical prognosis." (PMID 34484860, 2021). "To investigate the role of EFNA4 in the pathogenesis and development of liver cancer, we overexpressed EFNA4 in HCC cell lines Hep3B and Huh7." (PMID 34484860, 2021). "In this study, we found that the expression of EFNA4 was significantly increased in tissue sections obtained from patients with liver cancer." (PMID 34484860, 2021). "To further investigate the correlation between EFNA4 and liver cancer, we analyzed its expression in liver tumor arrays by immunohistochemistry (IHC)." (PMID 34484860, 2021). "Although EFNA4 has been shown to promote metastasis in liver cancer, the contradictory mechanism of its high expression and good prognosis in GC remains to be elucidated, which may involve its antagonistic effects with ETS1, and requires further exploration." (PMID 41162582, 2025). "Notably, the expression of EFNA4 in 90 tissue samples of liver cancer was related to the expression of alpha-fetoprotein (AFP; χ2 test, p = 0.0362) and the risk of vascular invasion (χ2 test, p = 0.0319)." (PMID 34484860, 2021).
choriocarcinoma (2 papers, 2018 to 2021). An aggressive malignant tumor arising from trophoblastic cells. "In this study, the low expression of EFNA4 suggests that it may not play a major role in miR-518a-3p-mediated metastasis of choriocarcinoma cells." (PMID 29367697, 2018).
chronic lymphocytic leukemia (2 papers, 2017 to 2021). "In chronic lymphocytic leukemia cells, ephrin-A4 activation by EphA2-Fc significantly reduced cell adhesion to fibronectin-, collagen-, laminin-, ICAM-1-, and VCAM-1-coated surfaces." (PMID 28851287, 2017).
oral cancer (2 papers, 2020 to 2021). "Interestingly, we found that EFNA4 was expressed in both tumor cells and tumor-infiltrating immune cells (unpublished data), suggesting that EFNA4 could be expressed by oral cancer cells and their associated stromal cells." (PMID 33436772, 2021). "In datasets of oral cancer gene expression, EFNA4 is upregulated in OSCC tissues compared with nontumor tissues and is correlated with later stage and angiolymphatic invasion of OSCC." (PMID 33436772, 2021).
ovarian tumor (2 papers, 2022). "A novel anti-EFNA4 drug (PF-06647263) binds specifically to EFNA4-expressing cells and subsequently induces DNA cleavage and apoptosis/cell death in triple-negative breast and ovarian tumors." (PMID 36052169, 2022). "An anti-ephrin-A4 antibody–drug conjugate, PF-06647263, achieved sustained tumor regression in triple-negative breast and ovarian tumor-initiating cells." (PMID 36077763, 2022).
triple-negative breast carcinoma (2 papers, 2021 to 2022). An invasive breast carcinoma which is negative for expression of estrogen receptor (ER), progesterone receptor (PR), and human epidermal growth factor receptor 2 (HER2). "EFNA4 may be a promising target for identification of tumor-initiating cells in triple-negative breast cancer and ovarian cancer." (PMID 33436772, 2021).
colon tumor (1 paper, 2022). "By characterizing proteins secreted by colon tumor cells, a previous study found that EFNA4 was abundant in the LIM1215 cell culture media and interstitial fluid, supporting its potential role in CRC biology." (PMID 35805033, 2022).
ependymoma (1 paper, 2024). A WHO grade II, slow growing tumor of children and young adults, usually located intraventricularly. "In 2005, research identified the overexpression of ephrin-A3, ephrin-A4, EPHB2, EPHB3, and EPHB4 in ependymoma tumor cells, either from frozen or formalin-fixed tumor samples, but the clinical impact remains unclear." (PMID 38612645, 2024).
heart failure (1 paper, 2021). Inability of the heart to pump blood at an adequate rate to meet tissue metabolic requirements. "It is, however, noteworthy that EFNA4, EFNA5 as well as TNFRSF1α were among the upregulated proteins of a correlation network uniquely associated with the regulation of actin filament process, ephrin receptor signaling, and regulation of muscle system processes in a heart failure study." (PMID 33572894, 2021).
hepatitis C virus infection (1 paper, 2021). A viral infection caused by the hepatitis C virus. "Thus, we extracted public databases and found that the expression of EFNA4 was significantly upregulated in HCC patients with hepatitis B virus (GenBank: GSE121248) and hepatitis C virus infection (GenBank: GSE107170), followed by activation of some tumor-related signaling pathways." (PMID 34484860, 2021).
Lymph Node Metastasis (1 paper, 2022). "The amplified and up-regulated gene EFNA4 is closely associated with lymph node metastasis." (PMID 36077763, 2022). "Moreover, we found that EFNA4 overexpression is linked to lymph node metastasis in LUAD." (PMID 36077763, 2022).
malignant peripheral nerve sheath tumor (1 paper, 2022). Malignant peripheral nerve sheath tumor (MPNST) is a rare and often aggressive soft tissue sarcoma occurring in a wide range of anatomical sites. "They detected an upregulation of miR-210 in malignant peripheral nerve sheath tumors (MPNST) going with a downregulation of EFNA4 and augmented proliferation and colony formation and migration." (PMID 35408800, 2022).
metastatic disease (1 paper, 2025). "Finally, we identified the EPHs (EPHA2, EPHA4, EPHA8, and EPHB4) and EFNs (EFNA1, EFNA3, EFNA4, and EFNB2) that are significantly overexpressed in the aggressive epithelioid histological subtype and revealed that the majority of EPHs/EFNs are overexpressed in metastatic disease." (PMID 41516312, 2025).
non-small cell lung carcinoma (1 paper, 2021). A group of at least three distinct histological types of lung cancer, including non-small cell squamous cell carcinoma, adenocarcinoma, and large cell carcinoma. "In addition, the elevated expression of Eph-A4 in non-small cell lung carcinoma patients is also found to be significantly associated with favourable prognosis 44, which is similar to our finding about ephrin-A4." (PMID 34093807, 2021).
promyelocytic leukemia (1 paper, 2017). "Moreover, EphA2 and EphA4 expression was induced, and ephrin-A4 expression was upregulated, in a human promyelocytic leukemia cell line, HL60, along with monocyte differentiation toward the classical CD14++CD16− monocyte subset." (PMID 28851287, 2017).
thyroid cancer (1 paper, 2022). "High expression of EFNA4 was distinctly positively correlated with the “cell cycle,” “DNA replication,” “thyroid cancer,” “NOTCH signaling pathway,” and “WNT signaling pathway”." (PMID 36052169, 2022).